AHR (aryl hydrocarbon receptor)
Diseases named in the same sentence as AHR in open-access papers (continued):
Sharing a sentence is not in itself a finding about the gene and the disease.
tumor (continued). "One of the best described roles of AhR is the tumor promoting action of 2,3,7,8-tetrachlorodibenzo-p-dioxin (TCDD)." (PMID 37696458, 2023). "In vivo evidence has demonstrated that AhR can function as a tumor suppressor in multiple cancers, including lung, breast, liver, prostate, skin, and different cancers of the intestine, hematopoietic system, and brain." (PMID 37106727, 2023). "The aryl hydrocarbon receptor (AhR) is overexpressed in many tumor types and exhibits tumor-specific tumor promoter and tumor suppressor-like activity." (PMID 38651159, 2023). "The intent of this review was to specifically address the biological and molecular contexts where AhR acts as a tumor suppressor in order to provide a framework for targeting AhR as a therapeutic strategy." (PMID 37106727, 2023). "Analysis of the TCGA database revealed higher expression levels of TET3 and AHR in tumor tissue compared to normal tissue in THCA." (PMID 37718440, 2023). "Trp metabolism yields metabolites that activate the aryl hydrocarbon receptor, which enhances the aggressiveness of the tumor and suppresses antitumor immunity." (PMID 37148546, 2023). "Together, these results suggested that sulfenylated AHR–regulated glycogenolysis promotes drug resistance in tumor cells in vivo." (PMID 38099490, 2023). "Several studies have investigated the main mechanisms of AHR-regulated cancer development and the relationship between abnormal AHR expression and tumours." (PMID 37760608, 2023). "AhR has been suggested to be a promoter of tumor cell development and progression, but this view is controversial." (PMID 37747052, 2023). "This would suggest thatregulating the expression of AhR plays an important role in tumor aggression." (PMID 37999261, 2023). "Tumor cells elicit AHR expression and activation in macrophages through the release of IL-1β/IL-6 and Kyn, respectively." (PMID 37394584, 2023). "For example, GR driven SGK1, seems to induce a cancer stem-like phenotype, suggesting a possible impact on tumor pathogenesis, in association with heightened TDO/kynurenine/AhR mediated rise in the NAS/melatonin ratio in microenvironment cells." (PMID 37970210, 2023). "Certain molecules that bind to AhR elicit tumor-suppressive effects (e.g., selective growth inhibition of cancer cells, apoptosis)." (PMID 37106727, 2023). "The data from the current report provide a new support to the tumor suppressor-like property of AHR that negatively regulates the TGFβ and other oncogenic signaling in cellular response to As3+." (PMID 37151890, 2023). "The latest research shows that benzopyrene, found in cigarette smoke and air pollutants, can induce programmed death-ligand 1 expression in lung epithelial cells through AhR; thus, it escapes the body's adaptive immunity, promoting tumor occurrence." (PMID 37056388, 2023). "Specifically, indole-3-pyruvic acid (I3P) and indole-3-aldehyde (I3A) catalyzed by IL4I1 in tumor activated AHR signaling through receptor-ligand binding, leading to increased motility of cancer cells and diminished proliferation of cytotoxic CD8+ T cells." (PMID 37507432, 2023). "In particular, AhR is overexpressed and constitutively activated in advanced BC neoplasm and was shown to drive tumor progression." (PMID 37447165, 2023). "Several models of AhR inhibition or overexpression have demonstrated that the constitutive AhR displays varying activities in cancer ranging from tumor-promoting to tumor-suppressing activities." (PMID 37241719, 2023). "The AHR is a key regulator of tumor progression by modulating both tumor cell intrinsic malignant properties as well as anti-tumor immunity." (PMID 37696456, 2023). "Like IDO1, TDO2-mediated Kyn promotes tumor immune suppression through AhR-signaling in various cancer types." (PMID 37876966, 2023). "The eukaryotic initiation factor 2 (EIF2) signaling, AHR, and tumor microenvironment pathways were identified as significantly negatively regulated." (PMID 37357228, 2023).
tumor (continued). "In recent studies, the dysregulated kynurenine metabolism, IDO expression, and AHR pathway activation in cancer patients’ blood contribute to immune evasion and tumour progression." (PMID 37760608, 2023). "In the context of cancer, the AhR has been shown to promote cell migration, angiogenesis, and tumor proliferation." (PMID 37408267, 2023). "During tumor growth, large amounts of Kyn are released to the periphery, enter MEPs and bias their differentiation into megakaryocytes by activating AhR." (PMID 37919525, 2023). "The animal model study also revealed that inhibition/inactivation of AhR or Biseugenol-induced Calpain-10-activation suppressed the growth of tumor mass and reduced the frequency of peritoneally disseminated cancer cells." (PMID 37830596, 2023). "Delineating the molecular contexts where AhR exerts tumor suppression is important for both chemoprevention and therapeutic targeting of the receptor." (PMID 37106727, 2023). "Upon binding to various ligands, AHR dimerizes with cofactors and translocates to the nucleus, where it initiates the transcription of downstream targets that are important for tumor initiation, proliferation, and metastasis." (PMID 37988371, 2023). "Like HIF, AHR can also be modulated by the tumour microenvironment and has critical roles in cancer progression, tumour aggressiveness, patient prognosis, and in tumour immunity." (PMID 36725335, 2023). "Upon entering tumor cells, drug molecules induce considerable ROS production, which triggers the AHR/glycogen phosphorylase/glycogenolysis/PPP pathway, leading to NADPH generation and subsequent ROS clearance as well as drug resistance." (PMID 38099490, 2023). "As expected, tumor growth slows and tumor cell apoptosis increases significantly in DLD-1/AhR-/- tumour-bearing mice compared with that in DLD-1 tumour-bearing mice." (PMID 37781044, 2023). "In general, kynurenine, as an endogenous ligand of AhR, can induce AhR activation when generated in the tumor microenvironment." (PMID 37999261, 2023). "Comparable results revealed that activation of AhR by the polyphenol carbidopa augments AR degradation and suppresses tumor growth of LNCaP cells in vivo." (PMID 37241719, 2023). "IFN-γ also induces tumor-repopulating cells (TRCs) to enter dormancy by an IDO1-Kyn-aryl hydrocarbon receptor (AhR)-p27 dependent pathway in TME with TRCs expressing high levels of IDO1 and AhR." (PMID 37380989, 2023). "We then examined the location and expression of Ki67 and PCNA by immunohistochemistry in the tumor tissues of ApcMin/+ mice and ApcMin/+ AhR -/- mice." (PMID 37781044, 2023). "Molecular research suggests that transcription factors CREB1, AHR, and TOX drive tumor growth and metastasis and are associated with poor prognosis of DLBCL." (PMID 38099311, 2023). "Inhibition of AhR was shown to suppress IDO/TDO mediated tumor progression, which synergizes with PD-1 blockade." (PMID 37277776, 2023). "By highlighting the targets and biological contexts of AhR-dependent tumor suppression, this review also provides a framework for combination studies and investigations of novel therapeutic approaches via the modulation of AhR." (PMID 37106727, 2023). "Several investigations have provided evidence supporting the potential tumor‐suppressive role of AhR under certain circumstances." (PMID 37747052, 2023). "Remarkably, sustained transcriptional activation of AHR was reported to facilitate tumor development and impairs the anti-tumor immunity." (PMID 37968758, 2023). "The AhR inhibits growth of colonic stem cells, and this is also consistent with the tumor suppressor like activity of this receptor." (PMID 38651159, 2023). "There are significantly different and ostensibly conflicting reports of AhR functioning as either a pro-tumorigenic or a tumor-suppressive factor in cancer, and this has been reviewed." (PMID 37106727, 2023).
tumor (continued). "Kynurenine supports tumor growth by acting as the ligand for the aryl hydrocarbon receptor-transcription factor that activates oncogenic growth." (PMID 38283944, 2023). "An emphasis has been placed on cancer types where there are in vivo studies supporting AhR-dependent tumor suppression." (PMID 37106727, 2023). "Identification of novel select modulators of AhR-regulated transcription that promote tumor suppression is an active area of investigation." (PMID 37106727, 2023). "In summary, the literature supports the conclusion that activation of AhR generates a pro-tumorigenic microenvironment that tumors evolve to escape the immune response, enabling progressive tumor growth and metastasis." (PMID 37696458, 2023). "Because the IDO–kynurenine–AHR axis produces immunosuppression via DCs and Tregs and thus limits autoimmunity, it also promotes tumor formation and progression." (PMID 37296860, 2023). "Kyn not only inhibits the anticancer immune response by inhibiting the proliferation of functional T cells but also constitutively activates AhR, which has been confirmed as an effective contributor to tumor progression and EMT." (PMID 37138031, 2023). "By modulating both tumor cell intrinsic malignant properties as well as anti-tumor immunity, AHR can promote the progression of tumors." (PMID 37696456, 2023). "Others have also reported that AhR has an important role in tumor development 7, 12 and that inhibiting its signaling pathway with AhR antagonists significantly inhibited the malignant evolution and invasion of tumors 13-15." (PMID 37056388, 2023). "Below, we review and discuss the tissue- and cancer-specific contexts where AhR has been shown to suppress carcinogenesis and inhibit tumor growth." (PMID 37106727, 2023). "In T cells, Kyn binds to the aryl hydrocarbon receptor (AHR), which inhibits the anti-tumor immune response of T cells and promotes the proliferation of cancer cells." (PMID 37047148, 2023). "An increasing number of studies show that there are overlaps between the HIF-1α and AhR pathways in terms of the control over biological functions, including tumor progression." (PMID 37305351, 2023). "Before planning future clinical trials, it is important to consider that, in the absence of chemotherapy, indoles or other tryptophan metabolites can impair the development of anti-tumour immune responses through the AhR in PDAC16." (PMID 36813961, 2023). "The aryl hydrocarbon receptor (AhR) is activated by Trp catabolites to enhance tumor malignancy and suppress anti-tumor immunity 20,21." (PMID 37781044, 2023). "Compound mutant (ApcMin/+ AhR -/-) mice showed significant decrease in tumor multiplicity when compared with the single transgenic littermates." (PMID 37781044, 2023). "Multiple studies have supported a tumor-suppressive role for the expression of AhR in cancers of the intestine, and AhR has emerged as a key regulator of intestinal homeostasis." (PMID 37106727, 2023). "Our previous studies have demonstrated that both tumor cells and immune cells mobilize the tryptophan–Kyn–AhR circuitry to dampen antitumor immunity, and high levels of Kyn are present in the peripheral blood of individuals with cancer." (PMID 37919525, 2023). "In LnCaP xenografts, activation of AhR by the tryptophan metabolite 2-(1′H-indole-3′-carbonyl)-thiazole-4-carboxylic acid methyl ester (ITE) was found to potently suppress tumor growth." (PMID 37106727, 2023). "This is intriguing, because IDO1 catalyzes the conversion of Trp to Kyn, which can suppress T-cell activity and allow tumor cells to escape clearance by the immune system, particularly through Kyn-mediated aryl hydrocarbon receptor (AHR) activation." (PMID 37985999, 2023). "In this study, the analysis of public databases, including TCGA, revealed higher expression levels of TET3 and AHR in tumor tissue compared to normal tissue in THCA." (PMID 37718440, 2023).
tumor (continued). "TCDD is a potent stable ligand of AhR and a well-known toxic substance that enhances tumor formation in various organs." (PMID 37232717, 2023). "There are indications that AhR can function as a tumor suppressor in blood cancers, primarily through regulating the differentiation status of monocytic or lymphoid progenitors." (PMID 37106727, 2023). "Conversely, some studies have provided evidence for a tumor suppressor role for AhR, underscoring the complexity of the AhR pathway." (PMID 37408267, 2023). "Additional effects of AhR activation on inflammation, tumor microenvironment, cell-to-cell communication, cell proliferation and survival, are likely to occur also in these cases." (PMID 37696458, 2023). "In fact, tumor tissues release large amounts of Kyn to the periphery, which can be used by MEPs to activate AhR." (PMID 37919525, 2023). "AHR−/− or AhR heterozygous mice had significantly greater tumor incidence relative to their AhR wild-type counterparts in TRAMP backgrounds." (PMID 37106727, 2023). "Kyn, a typical ligand for AhR, has been reported to be elevated in individuals with cancer and in tumor-bearing mice." (PMID 37919525, 2023). "There was an evident increase in the levels of LINC00665, UCHL3, AhR and PD-L1, but miRNA-582-5p was downregulated in the tumor tissues derived from LINC00665-overexpressing cancer cells." (PMID 37830596, 2023). "In contrast, AHR composite scores were significantly lower in tumours compared with patient-matched normal kidney (P = 1 × 10−5)." (PMID 36725335, 2023). "More prominent apoptosis was found in tumor cells of IECs the ApcMin/+ AhR -/- mice than in the WT mice by TUNEL staining." (PMID 37781044, 2023). "Studies in Sonic Hedgehog (SHH) medolloblastomas unraveled that depletion of AHR drives tumor growth due to elevated activation of the TGFβ signaling and the enrichment of SOX2 positive cancer stem-like cells." (PMID 37151890, 2023). "Loss of AhR enhanced stem cell and tumor growth and in the AOM/DSS model AhR-dependent suppression of FOXM1 and downstream genes was important for AhR-dependent anticancer activity." (PMID 38651159, 2023). "Many tumors express high levels of the AHR and produce endogenous AHR agonists, thus taking advantage of AHR activation to promote tumor cell intrinsic malignant properties and to suppress anti-tumor immune responses." (PMID 37696456, 2023). "Subsequently, the genes detected in the TaqMan array were input into QIAGEN’s IPA software, which revealed that AhR communicates with various tumor suppressors and proto-oncogenes." (PMID 37027342, 2023). "Although several studies have indicated the tumor-enhancing role of constitutive AhR, more cancer-specific studies are required." (PMID 37241719, 2023). "Here, we summarized the tumor-suppressive mechanisms regulated by AhR with an emphasis on the endogenous functions of the receptor in opposing carcinogenesis." (PMID 37106727, 2023). "This function is associated with cancer immunosuppression and sustained activation of AhR, encouraging tumor growth, and affects immune defense." (PMID 37999261, 2023). "Previous studies reported that TET3 and AHR have multifunctional roles in tumor cell proliferation and invasion." (PMID 37718440, 2023). "Ruxolitinib inhibited JAK2/STAT3 signaling and eliminated the tumor sphere forming abilities of AhR-wild-type expressing-PC-9 cells." (PMID 37830596, 2023). "AHR is a well-established ligand-activated transcription factor that regulates multiple downstream targets that promote tumor growth." (PMID 37607000, 2023).
tumor (continued). "Icaritin, a prenylated flavonol glycoside, inhibits growth of MCF-7 cells in vitro and tumor growth in a xenograft model and downregulates ER expression in an AhR-dependent manner." (PMID 37241719, 2023). "ROS have also been shown to increase expression of the aryl hydrocarbon receptor (AhR), which enhances tumor growth and proangiogenic function of macrophages through further chemokine production." (PMID 37626871, 2023). "The overall results clearly confirm the tumor suppressor-like activity of the AhR in the colon and demonstrate the possible clinical applications of AhR agonists for treating this disease." (PMID 38651159, 2023). "In HepG2 xenografts, the activation of AhR by the tryptophan metabolite ITE was found to potently suppress tumor growth." (PMID 37106727, 2023). "This indicates that the endogenous tumor-suppressive activities of AhR become apparent in the context of oncogene activation and disabled function of the tumor suppressor genes." (PMID 37106727, 2023). "I3A, produced by the indole-3-pyruvic acid pathway and aromatic amino acid aminotransferase via the gut microbiota, can activate AHR to enhance tumour malignancy and suppress anti-tumour immunity." (PMID 37936070, 2023). "The current report unraveled a new mechanism of As3+ carcinogenesis, which suggests that As3+ is inhibitory for the tumor suppressor-like character of AHR, followed by the amplification of the oncogenic pathways of TGFβ, Nrf2 and others." (PMID 37151890, 2023). "It is believed that AhR activation by tumor-derived Kyn triggers a gene expression program that leads to paracrine immune cell suppression." (PMID 37999261, 2023). "T-cells can take up Kyn in the tumor microenvironment and activate AHR signaling to upregulate the expression of PD-1 on the T-cell surface." (PMID 37985999, 2023). "Small molecules that serve as AhR agonists have also been found to inhibit tumor invasion and metastasis in basal-like BC subtypes, which are known to resist endocrine therapy." (PMID 36831661, 2023). "IL4I1 promoted aryl hydrocarbon receptor (AHR)-driven malignant properties and suppressed anti-tumor immunity, even in the presence of immune checkpoint blockade (ICB) and IDO inhibition." (PMID 37507432, 2023). "A lucid understanding of the molecular pathways regulated by AhR in the context of tumor suppression is essential for targeting the receptor and defining the molecular vulnerabilities that engender sensitivity to the activation of AhR." (PMID 37106727, 2023). "The absence of AhR resulted in a decrease in TAM proliferation capacity and their extra cellular matrix (ECM) transcriptional signaling, indicating that AhR was a key driver of the pro-tumor phenotype of TAMs." (PMID 37943609, 2023). "All 12 Low AHR group patients had more advanced tumours (T3 and T4 stage), whereas 8 out of 18 patients from the High/Medium AHR group had early stage (T1 and T2) tumours." (PMID 37760608, 2023). "The cancer patient survival data provided another layer of vigorous support for the tumor suppressor-like activity of AHR." (PMID 37151890, 2023). "Understanding the molecular determinants of tumor suppression in response to the activation of AhR is particularly salient when considered against the background of kynurenine–AhR-dependent immune suppression." (PMID 37106727, 2023). "This study opens an avenue for understanding of AHR by its sensing ROS and maintaining redox homeostasis of cells, thus providing strategies to reverse tumor drug resistance." (PMID 38099490, 2023). "We next induced AhR overexpression and found that it decreased the tumor weight and decreased the number or percentage of cells exhibiting necrosis." (PMID 37596694, 2023). "Despite implications of AHR as an oncogenic factor, the tumor suppressor-like property of AHR had also been uncovered in several reports using a variety of experimental models." (PMID 37151890, 2023).